NLRP3 (NLR family pyrin domain containing 3)
Diseases named in the same sentence as NLRP3 in open-access papers (continued):
Sharing a sentence is not in itself a finding about the gene and the disease.
Stroke (continued). "It is also demonstrated that NLRP3 inflammasome expression is enhanced in ischemia-like conditions like stroke patients." (PMID 34301174, 2021). "This study exposes NF-κB signaling and NLRP3 activation as a novel therapeutic target and curcumin as a novel therapeutical agent for stroke." (PMID 34630845, 2021). "At 1 day after stroke, macrophages took up the highest part of NLRP3+ (N: 15.26 ± 13.31%; DC: 4.75 ± 4.90%; M: 38.74 ± 25.65%, P < 0.001) or IL-1β+ (N: 21.80 ± 20.52; DC: 5.27 ± 4.13; M: 47.36 ± 29.30, P < 0.001) cells in patients' blood." (PMID 33967935, 2021). "Curcumin treatment remarkably reduced NLRP3 inflammasome and consequently ameliorated microglial pyroptosis following stroke (, –5)." (PMID 34630845, 2021). "Overall, the evidence indicates that cathepsins play key roles in NLRP3 activation, which provides new ideas for stroke treatment." (PMID 34059091, 2021). "Altogether, posttreatment of curcumin attenuates stroke-induced white matter damage through suppression of NF-κB signaling and inhibition of NLRP3 inflammasome." (PMID 34630845, 2021). "Our results indicate that the suppression of NLRP3 inflammasome activation after ISO pretreatment plays an important role in protecting the retina from stroke–induced retinal injury in diabetic mice." (PMID 34305534, 2021). "ERS and autophagy, through NLRP3 inflammation, influence the death of neurons after stroke and together act on cells to produce comprehensive and complex effects." (PMID 34059091, 2021). "Experiment of mice stroke model showed that NLRP3 was involved in BBB breakdown and the formation of brain edema, but this association has not yet been verified in clinical settings." (PMID 34493232, 2021). "In previous as well as in the present study, we have shown the potential of global NLRP3 inhibition to stabilize the BBB in an in vivo stroke model." (PMID 34930895, 2021). "We found that NLR family pyrin domain containing 3 (NLRP3) was the most studied, followed by NLRP1, NLRP2, and NLRC4 among the inflammasomes associated with stroke." (PMID 34233704, 2021). "Liu and his research team found that the NLRP3 inflammasome inhibitor provides a neuroprotection effect in stroke through TLR4/NF-κB/NLRP3 signaling pathway." (PMID 32908485, 2020). "The activation of the NLRP3 inflammasome aggravates the cerebral damage of stroke, whereas NLRP3 depletion protects mice from cerebral ischemia injury." (PMID 32625078, 2020). "Evidence has suggested that inhibition of NLRP3 activation attenuates infarction volumes and ameliorates stroke outcomes." (PMID 32788872, 2020). "Genetic modulations of NLRP3 impression in the stroke animal model bring out significant protection against microglia-related inflammatory responses." (PMID 32908485, 2020). "Regarding the dynamic change in NLRP3 after stroke in reproductively senescent mice, we found a gradual increase in NLRP3 over 24 h in microglia after brain ischemia." (PMID 32625078, 2020). "In contrast to the studies using a murine stroke model, we found a reduction of NLRP3 in the brain of rats." (PMID 32645874, 2020). "Although our understanding of NLRP3 inflammasome has gradually increased in recent years, we need more studies to further clarify the detailed mechanism of NLRP3 in the process of stroke in the future." (PMID 32581721, 2020). "NLRP3 inflammasome is involved in the initiation and development of several pathophysiological processes of CNS injury including stroke, neurodegenerative disease, and multiple sclerosis." (PMID 32733353, 2020). "Our findings support that Ki20227 made neuroprotection through downregulating microglia M1 phenotype and NLRP3 pathways with microglia M2 phenotype activation to improving neuron behavioral recovery in stroke." (PMID 32908485, 2020).
Stroke (continued). "The inhibitory effect of Gen on NLRP3 after brain ischemia injury has rarely been reported, particularly in postmenopausal stroke." (PMID 32625078, 2020). "Recently, gasdermin D and NLRP3 have been identified as programmed death patterns of stroke cell inflammation and pyrolysis." (PMID 32655760, 2020). "Compared with sham and normal groups, the NLRP3, NF-κB, and cleaved caspase 1 protein expression increased significantly in both stroke group and stroke+PBS group (∗∗∗P < 0.001)." (PMID 32908485, 2020). "Results revealed NLRP3 inflammasome was activated in the ischemic brain of stroke and stroke+PBS groups with high NLRP3 protein expression (∗∗∗P < 0.001)." (PMID 32908485, 2020). "There was a marked inflammatory response after stroke characterized by increased expression of proinflammatory cytokines and NLRP3 and by recruitment of leukocytes to the injured tissue." (PMID 31009361, 2019). "RP‐1127, an intravenous formulation of the NLRP3 inflammasome inhibitor glyburide, is being tested in a clinical trial for stroke (EudraCT 2017‐004854‐41) after a positively evaluated pilot study (ClinicalTrials.gov: NCT01268683)." (PMID 31015277, 2019). "The links between NLRP3 inflammasome activation, microglia/macrophage polarization and stroke also need to be elucidated." (PMID 31920554, 2019). "A randomized, controlled, double-blind clinical study of diabetic patients with stroke that focuses on inhibiting the NLRP3 inflammasome is anticipated." (PMID 31174550, 2019). "Using a mouse middle cerebral artery thrombosis model, we examined the inflammatory response after stroke and the contribution of the NLRP3 (NACHT, LRR and PYD domains-containing protein 3) inflammasome to ischemic injury." (PMID 31009361, 2019). "Recently, a small-molecule NLRP3 inhibitor MCC950 has been shown neuroprotective effect in stroke, cerebral hemorrhage, and TBI models." (PMID 30975164, 2019). "All in all, these results indicate that cigarette smoke-induced stroke exacerbation involves NLRP3 inflammasome activity." (PMID 31787973, 2019). "NLRP3 inflammasome have been demonstrated to significantly increase brain injury and neuroinflammation after stroke." (PMID 31920554, 2019). "Suppression of ER stress and/or ROS generation has also been found to alleviate NLRP3-mediated inflammation in stroke." (PMID 29662437, 2018). "In an attempt to define relevant pharmacological tools, Fann’s research team later introduced intravenous immunoglobulin as a protective approach against experimental stroke by a mechanism involving suppression of NLRP3-inflammasome activity." (PMID 29654318, 2018). "The present study concludes that MCC950 shows appropriate in vivo efficacy to repress NLRP3/Caspase-1/IL-1 signaling enough to improve acute stroke outcomes in a MCAO model of stroke." (PMID 29654318, 2018). "An inflammatory cascade of diabetic cerebral ischemia induces a series of complex changes in intracellular homeostasis, and NLRP3 inflammasome is an important factor in inflammatory after stroke." (PMID 29853850, 2018). "In ischemic or hemorrhagic stroke models, expression of the NLRP3, a known microglial inflammasome component, was increased, and specific blockade of NLRP3 reduced stroke induced neural damage and functional deficits." (PMID 29410649, 2018). "Conspicuously, recent randomized trials imply people with some specific NLRP3 genotype has been shows more prone to stroke and transient ischemic attacks." (PMID 29654318, 2018). "The NLRP3 inflammasome is an important component in innate immune response, and contributes significantly to ischemic brain injury following stroke." (PMID 29662437, 2018). "In the last years, the role of inflammasomes, particularly NLRP3, has been recognized in postischemic inflammation after stroke." (PMID 27127546, 2016). "Numerous studies have shown that NLRP3 is elevated in the brain of human stroke patients and experimental stroke animals." (PMID 27843532, 2016).
Stroke (continued). "So far, a number of recent studies focused on pathophysiological mechanism and/or potential therapeutic strategy to modulate inflammatory and oxidative stress pathways involving NLRP3 inflammasome in stroke brain damage." (PMID 27127546, 2016). "Pharmacological targeting of either the NLRP1 or NLRP3 inflammasomes has been shown to reduce innate immune responses and reduce infarct size post-stroke." (PMID 26690125, 2015). "The number of NLRP3-positive cells before EVT predicts stroke outcome after 3 months." (PMID 41923625, 2026). "Several studies have shown that the relation between the use of opioids and the inflammasome activation and activated NLRP3 inflammasome may affect the severity of a stroke." (PMID 39753298, 2025). "In stroke pathology, MNPs are associated with capillary obstruction, ferroptosis through reduced ZO-1, Fe2+ accumulation, and lipid peroxides and pyroptosis activation through ASC/NLRP3/GSDMD activation." (PMID 41303677, 2025). "Further, the KG diet upregulated the HIF-1α and interleukin (IL)-10 expression and inhibited thioredoxin-interacting protein (TXNIP), NOD-like receptor family pyrin domain-containing 3 (NLRP3) inflammasome activation and pro-inflammatory cytokine expression compared to SD-fed mice after stroke." (PMID 40272769, 2025). "However, earlier research has shown that in experimental stroke models, NLRP3 genetic deletion can lessen neuroinflammation and ischemic injury." (PMID 40272769, 2025). "Consequently, contemporary research on protective mechanisms against stroke injury has increasingly focused on regulating the NLRP3 inflammasome." (PMID 39690856, 2025). "NLRP3 inflammasome can activate caspase-1 state to cleaved, which in turn exposes the N-terminal of GSDMD for pore formation in cell membrane and promotes secretions of IL-1β and IL-18, causing serious of outcomes in stroke." (PMID 40289983, 2025). "In addition, a series of natural chemical substances play important roles in models of stroke by inhibiting NLRP3 inflammasome signaling." (PMID 40075143, 2025). "In addition to the acute injury, inflammation after stroke contributes to secondary cell injury, mediated, at least in part to NLRP3 inflammasome formation in microglia, MΦs located within the perivascular space, and endothelial cells themselves." (PMID 38550920, 2024). "This study emphasizes the detrimental effect of trained immunity on recurrent stroke and highlights the critical role of NLRP3 in mediating the formation of this memory, which may offer a potential therapeutic target for mitigating recurrent strokes." (PMID 38216560, 2024). "Additionally, MCC950, a small-molecule NLRP3 inhibitor, improved cognitive function and vascular integrity post-stroke." (PMID 39764140, 2024). "Moreover, inhibiting the NLRP3 inflammasome activation was also found to improve cognitive functions in the chronic phase of stroke." (PMID 38421089, 2024). "Furthermore, the knockout of NLRP3 in microglia alleviated the trained immunity and reduced the harmful effects of microinfarcts on recurrent stroke." (PMID 38216560, 2024). "Therefore, the NF-κB/NLRP3/Caspase-1/GSDMD pathway is involved in cerebral ischemia-reperfusion damage after stroke." (PMID 39199474, 2024). "However, the expression of cleaved caspase-3 was significantly attenuated after stroke treatment with a P2X7R antagonist (BBG) or an NLRP3 inhibitor (MCC950), which significantly reduced brain infarct volume, neuronal apoptosis, and nerve damage." (PMID 38601463, 2024). "Besides the strengths of our investigation, additional studies are necessary to finally evaluate the effects of NLRP3 inflammasome inhibition especially in the early phase (24–72 h) post stroke." (PMID 36600259, 2023). "The disease‐driven role of NLRP3 suggest that NLRP3 blockers have therapeutic potential for stroke." (PMID 37125240, 2023).
Stroke (continued). "Hypoxia-inducible factor-1α (HIF-1α) may modulate the inflammatory response through the NLRP3 inflammasome complex, thereby affecting pyroptosis after stroke." (PMID 38102696, 2023). "Curcumin not only reduces the expression of pro-inflammatory factors and promote M2 microglial polarization after stroke but also suppresses microglial pyroptosis and ameliorates stroke-induced white matter injury by inhibiting the NF-κB/NLRP3 signaling pathway." (PMID 36979506, 2023). "Existing research indicates that several inhibitors of localized death targeting cystein, NLRP3, and upstream pathways could minimize stroke-related brain tissue damage." (PMID 37435058, 2023). "However, the effects NLRP3 inflammasome activation and pyroptosis after stroke were attenuated by IPC, which decreased the expression of NLRP3, ASC, cleaved caspase 1, and GSDMD-N and reduced the production of IL-1β and IL-18." (PMID 37371374, 2023). "NLRP3 inflammasome is another important inflammatory pathway that is activated in stroke." (PMID 37047299, 2023). "Furthermore, investigation is warranted to determine SG formation on NLRP3 inflammasome activation in response to early RIC after stroke." (PMID 37580991, 2023). "Taken together, we could show that the inhibition of the NLRP3 inflammasome in the acute phase of IS directly influences post stroke inflammation in the ischemic penumbra." (PMID 36600259, 2023). "Interestingly, NLRP3 immunoreactivity dominantly increased in our stroke model compared to the NLRP1 inflammasome." (PMID 37822799, 2023). "The immunofluorescence and western blot results demonstrated that apocynin inhibited the NLRP3 inflammasome and promoted angiogenesis at 3 days but promoted the NLRP3 inflammasome and inhibited angiogenesis at 7 and 14 days after stroke, which was mediated by regulating autophagy activation." (PMID 35836200, 2022). "Cosin-Roger and his colleagues discovered one binding site for HIF-1α at −150 in the NLRP3 promoter through chromatin immunoprecipitation; HIF-1α regulates inflammatory responses through the NLRP3 inflammasome, thus influencing both apoptotic and pyroptotic cell death after stroke." (PMID 35132350, 2022). "Similarly, we demonstrated that the NOX2 inhibitor apocynin increased angiogenesis and reduced the NLRP3 inflammasome in the acute phase of stroke but suppressed angiogenesis and promoted NLRP3 inflammasome activation in the later stage of stroke." (PMID 35836200, 2022). "The evidence has shown that the pannexin-1 channel was an important mediator of neuroinflammation, and the inhibition of pannexin-1 could reduce NLRP3 inflammasome activation after stroke." (PMID 35401398, 2022). "The NLRP3 inflammasome may have a key role in detecting cellular damage and mediating inflammatory responses after stroke." (PMID 34866334, 2022). "However, information on the upregulation of NLRP3 will lead to a more robust inflammatory response in stroke is limited." (PMID 36232980, 2022). "After stroke, NLRP3-mediated inflammation is also activated in lung tissue." (PMID 35432726, 2022). "In this study, we determined the effect of NLRP3 knockout (KO) on ischemic brain and lung injury resulting from stroke by using a middle cerebral artery occlusion (MCAO) focal ischemia mouse model and attempted to further clarify the crosstalk between cerebral ischemia and ALI." (PMID 35432726, 2022). "A number of publications have reported different inflammasomes activation implicated in stroke, such as NLRP1, NLRP3, and AIM2, which contribute to activation of Caspase1 that shears the precursors of IL-1β and IL-18 into their mature forms (cl.IL-1β and cl.IL-18)." (PMID 35690810, 2022). "Studies in mice have shown that prophylactic protection against stroke by KO of NLRP3 improves brain damage, but whether NLRP3 alleviates peripheral organ injury induced by stroke is still unknown." (PMID 35432726, 2022).
Stroke (continued). "NLRP3 inflammasome and pro-inflammatory cytokines such as IL-1 β and caspase-1 were highly expressed in cellular and animal models of stroke, as well as in stroke patients." (PMID 36160384, 2022). "The possible mechanism might involve the regulation of pyroptosis via suppression NLRP3 inflammasome activation, meaning that the NLRP3 inflammation is a potential therapeutic target for stroke." (PMID 36311197, 2022). "More studies focusing on small molecular inhibitors of NLRP3 inflammasome or its downstream products could also draw similar conclusions that inhibiting NLRP3 inflammation contributed to the relief of brain injury and vicious neuroinflammation after stroke." (PMID 36204568, 2022). "EA via suppression of NLRP3 inflammasome could attenuate cerebral I/R neuroinflammation in stroke rats." (PMID 36238294, 2022). "We could recently show that NLRP3 inflammasome is upregulated early after stroke onset in neurons and glial cells, but also in endothelial cells (EC)." (PMID 35453512, 2022). "However, apocynin treatment significantly reduced NLRP3 expression on Day 3 after stroke but gradually increased NLRP3 levels from 7 to 14 days." (PMID 35836200, 2022). "After stroke, NLRP3 protein is abnormally activated, after which ASC is recruited." (PMID 34233704, 2021). "The NLRP3 inflammasome is a key intermediate, and treatments targeting upstream and downstream signaling pathways of NLRP3 may be novel strategies for stroke therapy." (PMID 34059091, 2021). "Finally, NLRP3-shRNA alone greatly attenuated stroke-induced white matter lesions and again enhanced curcumin neuroprotective effects." (PMID 34630845, 2021). "There was a trend of association between a higher level of serum concentration of NLRP3 and an increased risk of MBE in patients with acute ischemic stroke, possibly confounded by the severity of stroke, which is worth further investigation in large cohort studies." (PMID 34493232, 2021). "Our study suggested that curcumin reduced stroke-induced WM damage, improved functional outcomes, and attenuated microglial pyroptosis, at least partially, through suppression of the NF-κB/NLRP3 signaling pathway, further supporting curcumin as a potential therapeutic drug for stroke." (PMID 34630845, 2021). "Second, as suggested by animal study that the level of NLRP3 might be consistently increased within the first 24 h after stroke, we enrolled patients within 24 h after onset and examined their baseline NLRP3 level." (PMID 34493232, 2021). "Furthermore, a key focus of future research is to identify specific NLRP3 inhibitors and related mechanisms via our further study on NLRP3 inflammasome activation during a stroke." (PMID 32581721, 2020). "In recent, researchers have recognized a new inflammasome signaling pathway—NOD-like receptor pyrin domain containing 3 (NLRP3) inflammasome that may be a crucial mediator in detecting cell injury and mediating inflammation following stroke." (PMID 32581721, 2020). "More pain-related, Li and colleagues presented a meta-analysis, showing that the NLRP3 inflammasome plays a prominent role in post-stroke pain processing, and concluded that NLRP3 activation in thalamic and cortical microglia accounted for GABAergic alterations and thalamic lesions." (PMID 32466593, 2020). "Beside NLRP3, other inflammasomes are more frequently the focus of stroke research." (PMID 32645874, 2020). "Whether there is NLRP3 in astrocytes after stroke is still questionable, although very few in vitro studies suggested the NLRP3 increased in astrocytes, under lipopolysaccharide stimulation." (PMID 32625078, 2020). "However, the cell-specific expression of NLRP3 was not well understood, as diverse reports have previously indicated different cell-specific expression of NLRP3 after experimental stroke." (PMID 32625078, 2020).